CRP (C-reactive protein)
Diseases named in the same sentence as CRP in open-access papers (continued):
Sharing a sentence is not in itself a finding about the gene and the disease.
hookworm infection (3 papers, 2012 to 2017). "To determine the association of acute-phase proteins with hookworm infection, we measured the plasma levels of α-2M, CRP, haptoglobin, and SAA in INF and UN individuals." (PMID 23056659, 2012). "Blood samples were collected for assessing hemoglobin, serum ferritin, serum vitamin B12, serum folate, C-reactive protein, malaria infection and stool samples for assessment of hookworm infection." (PMID 24194926, 2013).
Hyperchloremia (3 papers, 2016 to 2023). An abnormally increased chloride concentration in the blood. "However, serum ferritin, CRP, D-dimer, and hemoglobin were not significantly correlated with hyperchloremia." (PMID 37520482, 2023).
hypersplenism (3 papers, 2022 to 2025). Overactive functioning of the spleen, resulting in excessive destruction of blood cells. "This outcome further supports the notion that fever and elevated CRP collectively reflect the underlying immune hyperactivation state in ROSAH syndrome and are associated with the mechanism of hypersplenism-mediated cytopenia." (PMID 41235249, 2025). "The CRP levels, representing the inflammation state, were within the normal range in the hypersplenism group, while in the asplenia/hyposplenism group were abnormally increased (p < 0.05)." (PMID 36105295, 2022). "However, the levels of inflammation indicators, such as hypersplenism, neutrophils, neutrophil to lymphocyte (NLR) ratios and C reactive proteins (CRP) of the HBV-HCC group were higher compared with HBV-LC group." (PMID 37201112, 2023).
Immunosuppression (3 papers, 2022 to 2025). "Increased tissue expression of NF‐κB and elevated serum concentration of CRP have been associated with intestinal inflammation in dogs with IBD (now re‐classified as immunosuppressant‐responsive enteropathy, which is a phenotype of chronic inflammatory enteropathy [CIE])." (PMID 40110597, 2025).
intracranial hypertension (3 papers, 2020 to 2023). A finding characterized by increased cerebrospinal fluid pressure within the skull. "A lower D0 hs-CRP was observed in patients with isolated intracranial hypertension (8.7 mg/L [IQR, 2.2-23.3]) and diffuse encephalopathy (31.0 mg/L [13.0-66.5]; P = .0045)." (PMID 37138790, 2023).
Intussusception (3 papers, 2021 to 2024). An abnormality of the intestine in which part of the intestine invaginates (telescopes) into another part of the intestine. "Compared with other parameters, such as the neutrophil count, CRP level and NLR level, the LCR was a more reliable indicator of intestinal resection in patients with intussusception." (PMID 34915876, 2021).
Legionella infections (3 papers, 2023 to 2025). "For these reasons URINELLA do not conclude that a CRP under 130 mg/L rule out definitely the diagnosis of LD; this result concerns only serotype 1 Legionella infections." (PMID 38530466, 2024).
leukoaraiosis (3 papers, 2014 to 2022). "Our patients had lower concentrations of fibrinogen and C-reactive protein and was also associated with a lower degree of leukoaraiosis (neuroimage associated with inflammatory response)." (PMID 35401421, 2022). "Elevated serum levels of C-reactive protein (CRP) have been associated with leukoaraiosis in elderly brain." (PMID 24587705, 2014). "We found that CRP levels are inversely associated with cognitive performance in coronary patients and this relation was independent of age, sex, educational attainment, and degree of leukoaraiosis." (PMID 24587705, 2014). "Our analysis demonstrated that only a small portion of the CRP influence on cognition was mediated via leukoaraiosis." (PMID 24587705, 2014). "The adjustment for the presence of leukoaraiosis little changed this variance (5.98%, P: 0.005), indicating that only a small portion of the CRP influence on cognition was mediated via leukoaraiosis." (PMID 24587705, 2014). "Assessing Pearson's partial correlation coefficients, controlling for age, sex, and educational level, we found negative correlation between CRP and MMSE (r: −0.268; P: 0.002) and positive correlation between CRP and presence of leukoaraiosis lesions on CT (r: 0.209; P: 0.017)." (PMID 24587705, 2014). "With these results we found that the CRP levels can explain 7.18% (P: 0.002) of the variance of ΔMMSE, and adjusting for leukoaraiosis this variance little changed (5.98%; P: 0.005), showing that little CRP influence on cognition was mediated by leukoaraiosis, as evaluated by CT scan." (PMID 24587705, 2014). "At first, we analyzed the degree of leukoaraiosis with ΔMMSE and CRP." (PMID 24587705, 2014). "It is unknown how the effect of CRP on cognition is mediated by leukoaraiosis." (PMID 24587705, 2014). "Mean CRP levels equaled +5.070 ± 2.71 for subjects with leukoaraiosis and +4.080 ± 1.82 for those without leukoaraiosis (P value: 0.025)." (PMID 24587705, 2014). "Moreover, the variance of CRP serum levels upon cognition (7.18%; P: 0.002) was independent of the degree of leukoaraiosis, because this variance little changed after adjustment for the later (5.98%; P: 0.005)." (PMID 24587705, 2014).
leukoplakia (3 papers, 2018 to 2026). A white patch or plaque on a mucous membrane that cannot be characterized clinically or pathologically as any other disease. "In the present study, based on the clinical diagnosis in group II patients, elevated serum CRP levels were evident in speckled leukoplakia and erosive OLP." (PMID 30842796, 2018). "The mean CRP levels were elevated in patients with PMDs (group II) when compared to group I. In group II, patients with OLP showed a higher mean CRP (10.52 mg/l) followed by patients with leukoplakia (3.35 mg/l) and OSMF (2.44 mg/l)." (PMID 30842796, 2018). "Group II included 15 patients with oral leukoplakia (group II A) with the mean ± SD CRP level of 3.35±2.41 mg/l, 10 patients with OLP (group II B) with the mean ± SD CRP level of 10.52±16.19 mg/l, and 5 patients with OSMF (group II C) with the mean ± SD CRP level of 2.44±1.93 mg/l." (PMID 30842796, 2018).
listeriosis (3 papers, 2022 to 2024). A bacterial infection caused by Listeria monocytogenes. "More research is needed to understand the relationship between CRP and in-hospital mortality from listeriosis." (PMID 39597753, 2024). "Patients with listeriosis frequently have increased CRP levels (up to 80%), but it remains unclear if these levels can predict in-hospital death." (PMID 39597753, 2024).
meningococcal disease (3 papers, 2014 to 2021). "Procalcitonin (PCT) has been shown in comparatively small studies to be a better diagnostic marker of bacterial infection in PICU than C-reactive protein (CRP) and to be a prognostic marker in meningococcal disease." (PMID 33544738, 2021). "Data to evaluate procalcitonin, C-reactive protein and white cell count tests as indicators of Meningococcal Disease were collected from six independent studies identified through a systematic literature search, applying PRISMA guidelines." (PMID 26053385, 2015). "The data included 881 children with fever without source in developed countries.The optimal cut-off value for the procalcitonin, C-reactive protein and white cell count tests, each as an indicator of Meningococcal Disease, was determined." (PMID 26053385, 2015). "In patients with meningococcal disease, high PTX3 and low CRP concentration at admission discriminated between presence and absence of shock." (PMID 25530683, 2014).
microcytic hypochromic anemia (3 papers, 2023 to 2025). "Laboratory tests revealed normal kidney function, serum electrolytes, C3, C4, prothrombin time (PT), partial thromboplastin time (PTT), microcytic hypochromic anemia (HGB 9.5, MCV 63), normal c-reactive protein (CRP), and elevated erythrocyte sedimentation rate (ESR)." (PMID 39868057, 2025).
mucinous adenocarcinoma (3 papers, 2013 to 2025). An invasive adenocarcinoma composed of malignant glandular cells which contain intracytoplasmic mucin. "Another meta-analysis that included 6 cohorts found that OC risk increased by 67% in women with CRP concentrations >10 mg/L increased CRP level, especially for endometrioid and mucinous carcinoma." (PMID 32000385, 2020).
myeloproliferative disorder (3 papers, 2014 to 2023). A clonal hematopoietic stem cell disorder, characterized by proliferation in the bone marrow of one or more of the myeloid (i.e., granulocytic, erythroid, megakaryocytic, and mast cell) lineages. "CRP also enhances thrombocytopenia and has been reported in other thrombocytosis-related diseases, and also, it possibly modulates the intrinsic risk of cardiovascular events in cases of myeloproliferative disorders." (PMID 37873776, 2023).
myocardial diseases (3 papers, 2019 to 2025). "Cardiac biomarkers such as hs-troponin I, NT-proBNP, and CRP are not disease-specific biomarkers, but they can aid in the diagnostic work-up of myocardial diseases." (PMID 40141814, 2025).
myonecrosis (3 papers, 2007 to 2025). "This group of 10 patients were older and displayed a lower platelet count (which remain normal), a more intense myonecrosis along with higher fibrinogen and C-reactive protein levels compared with patients with normal ADAMTS13 activity." (PMID 41160661, 2025). "On the other hand, STEMI and to a lesser degree NSTEMI, with their attendant myonecrosis are associated with higher levels of troponin, while CRP level is also elevated in these conditions but not to the same extent as troponin." (PMID 33886564, 2021). "It has been hypothesized that necrosis is a strong stimulus for CRP increase in patients suffering from myonecrosis." (PMID 17603914, 2007). "It is possible that ischaemic fat necrosis like in epiploic appendagitis might trigger an inflammatory response, which – similar to myonecrosis – results in the slight increase of CRP value." (PMID 17603914, 2007).
nephropathia epidemica (3 papers, 2009 to 2012). "Categorical variables associated with the severity of the disease in nephropathia epidemica patients, divided into four groups according to maximum plasma interleukin-6 and C-reactive protein levels." (PMID 20500875, 2010). "We found that offspring of patients with Balkan Endemic Nephropathy have higher CRP serum levels than offspring of parents without the disease." (PMID 19400955, 2009).
Neurodevelopmental delay (3 papers, 2020 to 2025). "Alcohol-exposed children with typical neurodevelopment (A/TD; resilient) showed activation of MIP-1β, MDC, and MCP-4 and inhibition of CRP and PlGF, with the opposing profile detected in alcohol-exposed children with neurodevelopmental delay (A/ND; at risk)." (PMID 31992316, 2020). "Thus, the activity of network 2 may be particularly important in predicting child risk vs. resilience, with elevated levels of MIP-1β, MDC, and MCP-4 potentially acting as protective factors, whereas elevated levels of PlGF and CRP potentially acting as risk factors for neurodevelopmental delay." (PMID 31992316, 2020).
neuropathic pain (3 papers, 2022 to 2025). Chronic pain caused by damage to nerve fibers. "Moreover, findings from neuropathic pain models—such as improvements in nerve conduction and reductions in pro-inflammatory cytokines (e.g., IL-6, TNF-α, CRP)—lend additional biological plausibility, although the certainty of this evidence remains limited." (PMID 41441449, 2025). "In psychogenic and neuropathic pain without elevated CRP, increased intakes of MUFA and eicosadienoic acid, a family member of n-6 fatty acids, appear to affect CP." (PMID 35720172, 2022).
nocardiosis (3 papers, 2020 to 2024). Nocardiosis is a local (skin, lung, brain) or disseminated (whole body) acute, subacute, or chronic bacterial infection. "Clinical symptoms, radiological findings and inflammatory parameters (including leukocytes, neutrophils, CRP, and PCT) play an important role in the diagnosis of nocardiosis but lack specificity." (PMID 36823137, 2023).
non-alcoholic fatty liver (3 papers, 2017 to 2025). A benign form of fatty non-alcoholic fatty liver disease where the disease has not yet progressed to the inflammation of liver. "Hazard ratios (95% CI) for the incidental rate of non-alcoholic fatty liver by the baseline hs-CRP level (Cox proportional hazard models)." (PMID 28234943, 2017).
nonischemic cardiomyopathy (3 papers, 2013 to 2025). Forms of cardiomyopathy that are not related to known coronary artery disease. "Ceruloplasmin was significantly elevated in patients with ischemic or nonischemic cardiomyopathy and had linear correlation with C-reactive protein and LVEF." (PMID 23781119, 2013). "When compared with the control group, both the ischemic and nonischemic cardiomyopathy groups were older, had higher levels of creatinine, uric acid, C-reactive protein, homocysteic acid, LVIDd, and LA, and had lower levels of high-density lipoprotein cholesterol and LVEF." (PMID 23781119, 2013). "The aim of this study was to assess the relationship between the inflammatory biomarkers, C-reactive protein (CRP), neopterin, and disease severity, as well as to evaluate the predictive value of these parameters for the outcome of HF patients with nonischaemic cardiomyopathy (CMP)." (PMID 31861167, 2019). "We concluded that CP levels were significantly high in patients with ischemic or nonischemic cardiomyopathy and had a positive linear correlation with C-reactive protein and a negative linear correlation with LVEF." (PMID 23781119, 2013).
oral candidiasis (3 papers, 2019 to 2024). Infection of the mucosal lining of the mouth with the fungus Candida albicans. "In terms of laboratory investigations, a significant association was observed between elevated levels of ferritin, C-reactive protein, and fibrinogen and the development of oral candidiasis in patients with SARS-CoV-2 infection." (PMID 39458399, 2024).
oral lichen planus (3 papers, 2020 to 2023). Oral lichen planus is a chronic inflammatory oral condition of unknown aetiology characterized by T-cell-mediated chronic immune response and abnormal epithelial keratinization cycle. "Data on lichen sclerosus are limited, but CRP can be elevated both in salivary and serum samples from oral lichen planus cases." (PMID 37873776, 2023).
oral submucous fibrosis (3 papers, 2023 to 2025). "Data on mouth cancer are few, yet prediagnostic concentrations of CRP have been associated with the subsequent development of oral cancer, and higher values were seen in squamous cell carcinoma, while lower values were recorded for leukoplakia, oral submucous fibrosis, and lichen planus." (PMID 37873776, 2023). "Nevertheless, another study concluded that CRP can be raised in oral submucous fibrosis, but there was no statistical significance compared to oral squamous cell carcinoma, in which values were significant and also showed a positive correlation with primary tumor size." (PMID 37873776, 2023).
orbital cellulitis (3 papers, 2022 to 2025). Inflammation of the eye tissues posterior to the orbital septum, and generally secondary to an infection spread from adjacent sinuses. "While these markers were non-specific, it has been suggested that CRP levels greater than 20.2 mg/l had a 90.9% sensitivity and 90.5% specificity in diagnosing orbital cellulitis when differentiating from NSOI in cases of uncertainty." (PMID 40475267, 2025). "However, there were not enough data for meta-analysis of orbital cellulitis morbidities: pain, periorbital edema, vision, ptosis, levels of C-reactive protein, and serum WBC levels in our analysis." (PMID 33722520, 2022).
osteonecrosis (3 papers, 2018 to 2024). A none disease characterized by death of bone tissue due to a lack of blood supply. "In pairwise comparison with Bonferroni correction for multiple testing, CRP in this group was significantly higher than in groups fracture (p < 0.001), oncology (p = 0.005), osteonecrosis (p = 0.017) and sialadenitis (p = 0.039)." (PMID 39304566, 2024). "Osteonecrosis by infectious osteomyelitis and elevation of the inflammatory factors C-reactive protein and IL-6 promoted by P. gingivalis s were also significantly reduced in the presence of silver-coated rods." (PMID 36319854, 2022). "CRP is an acute-phase protein, negatively correlated with adiponectin level in osteonecrosis of the femoral head." (PMID 29750162, 2018).
osteophytes (3 papers, 2015 to 2018). "We also attempted a cluster analysis of patients with similar DAS-28 scores using the following variables: age at scan; duration of symptoms; CRP; ESR; SH grades 1, 2 and 3; PD; presence of osteophytes; erosions; TJC; and SJC and GVAS." (PMID 27325125, 2016).
overlap syndrome (3 papers, 2021 to 2025). "In this study, the level of serum C-reactive protein, a marker of inflammation, was higher in patients with overlap syndrome than in patients with COPD alone, indicating that OSA increased body's inflammatory stress in patients with COPD." (PMID 34336955, 2021).
pancreatic neuroendocrine tumor (3 papers, 2023 to 2025). Pancreatic endocrine tumor, also known as pancreatic neuroendocrine tumor (PNET), describes a group of endocrine tumors originating in the pancreas that are usually indolent and benign, but may have the potential to be malignant. "In a subgroup analysis, albumin, CRP and GPS remained associated with OS in SI‐NET, pancreatic NET and NET of other origin." (PMID 38477040, 2025).
papillitis (3 papers, 2022 to 2023). "Fundus evaluation reveals optic disc edema, while blood tests detect elevated levels of erythrocyte sedimentation rate (ESR) and C-reactive protein (CRP)." (PMID 38006824, 2023).
Patent ductus arteriosus (3 papers, 2015 to 2021). In utero, the ductus arteriosus (DA) serves to divert ventricular output away from the lungs and toward the placenta by connecting the main pulmonary artery to the descending aorta. "Elevated CRP and/or IL-6 in clinical routine samples from cord blood were found in the high S100A group only, while the only significant difference regarding neonatal morbidities was a higher percentage in need of treatment for patent ductus arteriosus in the high S100A group." (PMID 32612607, 2020).
pemphigus (3 papers, 2022 to 2025). Pemphigus is a group of rare autoimmune diseases that cause blistering of the skin and mucous membranes (mouth, nose, throat, eyes, and genitals).This conditioncan occur at any age, but often strikes people in middle or older age. "Elevated CRP level suggested ongoing systemic inflammation, while the raised desmoglein-3 antibody levels indicated autoimmune blistering, favoring a pemphigus variant." (PMID 40809161, 2025). "Pemphigus disease area index (PDAI), IGC, IG%, C-reactive protein, neutrophil/lymphocyte ratios, platelet-to-lymphocyte ratio (PLR), anti-desmoglein 1, and anti-desmoglein 3 levels in patients with pemphigus were recorded retrospectively, and the statistical relationship between them was evaluated." (PMID 40068041, 2025).
perihilar cholangiocarcinoma (3 papers, 2016 to 2021). "More importantly, high CRP level was significantly correlated with poor survival and found to be independently predictive of survival in patients with perihilar cholangiocarcinoma as evidenced by the in the univariate and multivariate analyses." (PMID 27733196, 2016). "Already, a retrospective study has shown that the serum CRP was a prognostic factor in a patient with a small size perihilar cholangiocarcinoma." (PMID 27733196, 2016). "Besides, Saito and colleagues have reported that a prognostic scoring system, consisting of PLR, CRP, ALB and CEA, could predict the postoperative survival after resection of perihilar cholangiocarcinoma." (PMID 33676467, 2021).